TOP2A (DNA topoisomerase II alpha)
Diseases named in the same sentence as TOP2A in open-access papers (continued):
Sharing a sentence is not in itself a finding about the gene and the disease.
tumor (continued). "To further confirm whether HPV16 E6 regulated the CC cell progression through TOP2A expression, we found that knockdown of TOP2A inhibited proliferation, migration, invasion, and tumor growth and promoted the apoptosis in HPV16‐negative CC cells overexpressing HPV16 E6." (PMID 38205938, 2024). "Furthermore, we sought to analyze the effect of TOP2A inhibition on IL-6 protein expression, which is one of the key cytokines in the tumor microenvironment confer resistance to chemo and radiotherapy and its overexpression has been reported in almost all types of tumors." (PMID 38957610, 2024). "In addition, these CENPF-related genes exhibited the expression differences between normal and tumor tissues: the expression of TOP2A or KIF23 was significantly upregulated in LPS, while that of BAG1,PNPLA2, CRYL1 or GRN was significantly downregulated in LPS or MRCLPS compared to normal tissues." (PMID 37108172, 2023). "As TOP2A is highly expressed in numerous tumor types, it may act as an oncogene." (PMID 37818158, 2023). "However, the analysis of a large cohort of primary PCa and metastatic castration resistant PCa (CRPC) (333 and 118 tumours, respectively) revealed a significant positive correlation of both TOP2A and KDM1A levels with BAZ2A expression in both metastatic and primary tumors." (PMID 37184661, 2023). "TOP2A, on the other hand, displayed a ~2-fold reduction in its mRNA levels in both tumor cell lines and no significant change in HMECs, but protein levels were also inversely modulated, with a 2-fold reduction in both tumor cell lines and a 5-fold increase in HMECs." (PMID 37888205, 2023). "Interestingly, we encountered an inverse modulation of AURKA and TOP2A in tumor and normal breast cells, which could constitute the basis for treatment selectivity." (PMID 37888205, 2023). "Decreased TOP2A activity or expression may lead to tumour resistance to TOP2A inhibitors." (PMID 35711974, 2022). "Therefore, we investigated if TOP2A knockdown enhanced the anti-tumor effects of CPX in LUAD cells." (PMID 35251970, 2022). "Therefore, interactions between USP10, RNF168, and TOP2α may play a key role in the development of tumor resistance to TOP2 inhibitors." (PMID 36248971, 2022). "Moreover, assessment of TOP2A expression mainly at diagnosis may be discordant with TOP2A status at relapse, considering tumor heterogeneity and clonal evolution during progression." (PMID 30760286, 2019). "Indeed, tumor TOP2A expression is a strong predictor of the therapeutic response to anthracyclines and its reduction by DRZ could be deleterious." (PMID 25406834, 2014). "The IHC method for in situ determination of TOP2A has been extensively validated and shown to reflect closely the exact enzyme activity in formalin-fixed paraffin-embedded human tissues, leading to the prognostic and predictive importance of this test in other neoplasms." (PMID 23398928, 2013). "We also investigated whether amplification status of TOP2A is correlated with specific benefit from conventional-dose anthracycline-based chemotherapy compared to high-dose alkylating chemotherapy in patients with HER2-positive tumours." (PMID 17088909, 2006). "Our study revealed distinct cellular compositions and varying degrees of malignancy across different tumour regions, with the T1 region showing the highest malignancy and overexpression of HMGB2 and TOP2A." (PMID 40099956, 2025).
tumor (continued). "We identified five tumor EPC subtypes using cell markers: C0 TSPAN1+, C1 AKR1B10+, C2 TOP2A+, C3 PTPRC+, and C4 LRMP+." (PMID 40777026, 2025). "Using three spatially-enriched marker genes for each tumor subregion (CT: BCAN, CSPG5, TOP2A; Pseudo: HILPDA, IGFBP5, LGALS3; and MVP: MGP, LUM, THBS1) we identified distinct sub-populations of malignant cells from the scRNA-seq data." (PMID 41366031, 2025). "IHC analysis demonstrated that tumour cell markers, including HMGB2, TOP2A, CENPF, and TPX2, were strongly expressed in T1, with HMGB2 showing higher expression than TOP2A." (PMID 40099956, 2025). "The IHC results of Ki67 and TOP2A demonstrated that combination of UBE2C knockdown and doxorubicin treatment had the strongest anti‐tumor effect." (PMID 40729680, 2025). "We further investigated and analyzed the EPCs subtypes, categorizing them into C0 TSPAN1+ Tumor EPCs, C1 AKR1B10+ Tumor EPCs, C2 TOP2A+ Tumor EPCs, C3 PTPRC+ Tumor EPCs, and C4 LRMP+ Tumor EPCs." (PMID 40777026, 2025). "A network of interacting proteins was assembled to determine hub genes, and TOP2A and CDK1 were selected for immunohistochemical (IHC) validation in 76 SCCE tumor samples." (PMID 40765849, 2025). "In our study, despite the upregulation of TOP2A and CCNA2, miR-142-3p exhibited an overall tumor-suppressive phenotype, as evidenced by the inhibition of proliferation, survival, and migration pathways." (PMID 40362400, 2025). "While PCR validation on matched tumor/normal tissues confirmed significant differential expression of IFI27, KIF20A, KLK10, and TOP2A." (PMID 41008826, 2025). "The differing correlations of TOP2A and EPHB2 with immune infiltrates underscore their distinct roles in shaping the tumor microenvironment." (PMID 40958237, 2025). "At the same time, proliferative markers such as MKI67, TOP2A, PRC1 and RRM2 underscore the importance of cell-cycle dynamics not only in tumor growth but also potentially within rapidly expanding immune subsets that contribute to treatment efficacy." (PMID 40745034, 2025). "The results demonstrate that TNBCvax significantly inhibits and delays tumor development compared to the CpG group and other single vaccine-treated groups, including HIF-1α, IGF-1R, and TOP2A." (PMID 40969744, 2025). "The discovery that CDK1, TOP2A, AURKA, TPX2, BUB1B, and CENPF are key cell-cycle regulators in NSCLC emphasizes the ongoing contribution of mitotic dysregulation to tumor growth." (PMID 41080754, 2025). "Cluster 13 was exclusively expressed in T1, and the highly expressed markers TOP2A, CENPF, TPX2 and HMGB2 are related to tumour proliferation and malignancy." (PMID 40099956, 2025). "Concurrently, high tsMHC-II-expressing tumor cells exhibited a closed chromatin state at the ABCB1 promoter and an open state at TOP2A." (PMID 40495188, 2025). "The significant overlap highlights the dual roles of genes such as TOP2A, CCNB2, BUB1, TPX2, and EZH2 in both tumor initiation and tumor progression, reinforcing their potential as key biomarkers for PCa." (PMID 40626556, 2025). "A similar trend was observed for anti-TOP2A and anti-ACTR3 antibodies, which showed a significant decrease in positivity from early to late tumor stages (43-50% vs. 22-24%)." (PMID 40990023, 2025). "The expression of four genes (TOP2A, CDK1, CCNA2, and CCNB2) with high scores in module 1 were more in tumor samples and have been identified by GEPIA analysis." (PMID 38895552, 2024). "We extracted and re‐clustered ICC tumor cells and named those overexpressing MKI67, TOP2A, and UBE2C as proliferating tumor cells (Prolif)." (PMID 39716897, 2024).
tumor (continued). "We identified three subtypes in tumor cells, including ARG1+ metabolism subtype (Metab-subtype), TOP2A+ proliferation phenotype (Prol-phenotype), and S100A6+ pro-metastatic subtype (EMT-subtype)." (PMID 39095854, 2024). "TOP2A expression was considerably upregulated in NSCLC and significantly correlated with tumor metastasis and the occurrence of epithelial–mesenchymal transition (EMT) in NSCLC." (PMID 38806610, 2024). "It is noteworthy that PDRWH also identified known tumor-specific drivers that were missed by other methods, such as ABL2 for BRCA, SETBP1 for KIRC, NIN and TOP2A for STAD." (PMID 38683860, 2024). "Lastly, KCTD9 silencing was effective in the tumor tissues of mice injected with sh-KCTD9, and downregulation of KCTD9 led to the restoration of TOP2A protein expression." (PMID 38374109, 2024). "Collectively, these data indicate that HCC tumor cells can be stratified into three distinct subtypes, characterized by the expression of ARG1, TOP2A, and S100A6, respectively." (PMID 39095854, 2024). "Correlation analysis revealed a significant correlation of AURKA, AURKB, BUB1, HJURP, TOP2A, and TTK with tumor proliferation, G2M checkpoint, MYC targets, and DNA replication." (PMID 38726001, 2024). "In this context, we previously showed that ASncmtRNA KD induces an increase in miRNAs miR-4485 and miR-1973 and we are currently studying the significance of this effect on the genomic integrity of tumor and normal cells, especially focused on AURKA and TOP2A." (PMID 37888205, 2023). "Protein-coding genes with increased expression across all tumor types included E2F7, ETS1, EZH2, ID3/4, MKI67, PIK3R3, and TOP2A." (PMID 36865335, 2023). "Clinically, EZH2 and TOP2A are highly expressed, and miR-139-5p is expressed at low levels in HCC tumor tissues compared with adjacent normal tissues, which indicates a poor prognosis in patients with HCC." (PMID 38008711, 2023). "BALB/c nude mice were used to establish a xenograft tumor model and verify the phenotypes upon EZH2 and TOP2A silencing and miR-139 overexpression in vivo." (PMID 38008711, 2023). "Compared with adjacent normal tissues, the miR-139-5p level is lower in HCC tumor tissues; compared with low-EZH2 HCC, miR-139-5p expression was lower in high-EZH2 HCC; compared with low-TOP2A HCC, miR-139-5p expression was lower in high-TOP2A HCC." (PMID 38008711, 2023). "Regarding the protein levels of these genes, SLC2A1, MMP14, TOP2A, ANLN, and SLC22A3 exhibited higher expression in tumor samples compared to normal samples." (PMID 37604837, 2023). "The expression of CDK1, MKI67, TOP2A, and CEP55 was significantly higher in tumor tissue than in normal tissue." (PMID 38134110, 2023). "Top2A vaccination increased CD4+ and CD8+ tumor infiltrating lymphocytes as well as the percentage of the functionally activated CD4+ and CD8+ cells in the spleens from the vaccinated mice." (PMID 37880313, 2023). "The present study revealed that EZH2 and TOP2A mRNAs and proteins were overexpressed in HCC tumor tissues, and their overexpression was correlated with differential tumor grade, tumor invasion, TNM stage, and shorter survival in patients with HCC." (PMID 38008711, 2023). "More importantly, correlation analysis showed a positive relationship between TOP2A expression and PI3K-AKT-mTOR pathway, EMT markers, and tumor proliferation signature." (PMID 37980167, 2023). "Consistently, compared with normal tissues, EZH2 and TOP2A mRNA levels increased in HCC tumor tissues and expression of miR-139-5p decreased in HCC tumor tissues." (PMID 38008711, 2023). "TOP2α, undetectable in adult cardiomyocytes, is overexpressed in tumor cells, and DOX exerts cytotoxicity in tumor cells by forming Top2α-DOX-DNA complex, responsible for DNA breakage and tumor cell death." (PMID 37602332, 2023).
tumor (continued). "In conclusion, we identified TOP2A as a gene related to bone metastasis of LIHC and explored its relationship with poor prognosis and immunosuppressive tumor microenvironment of LIHC through a comprehensive analysis of bioinformatics." (PMID 37980167, 2023). "Moreover, via NBACs high affinity to TOP2α, NBACs may augment the anti-tumor effect." (PMID 37711551, 2023). "We reanalyzed the expression data of EZH2 and TOP2A in tumor tissues and paired normal tissues from 31 tumors in the TCGA database and found that EZH2 and TOP2A were highly expressed in various solid tumors, including HCC." (PMID 38008711, 2023). "It has been shown that TOP2A and Wnt3a play an essential role in the development of NSCLC and tumor metastasis, and the expression of TOP2A and Wnt3a is closely related to tumor differentiation, TNM stage and the occurrence of lymph node (LN) metastasis." (PMID 37407689, 2023). "We selected BIU-87 cells to evaluate the effect of down regulating TOP2A and KK47 cells to evaluate the effect of up regulating RRM1 to estimate the correlation between the expression of these two genes and tumour sensitivity to pirarubicin and gemcitabine." (PMID 35711974, 2022). "In many tumours, HER-2 and TOP2A are co amplified and expressed, indicating that the activation of multiple genes determines the biochemical activity and clinical characteristics of tumour cells." (PMID 35711974, 2022). "Through scRNA-seq analysis, we identified a cluster of proliferative tumor cells (hepatocytes C4), which had significant levels of KI67, TOP2A, and CENPF." (PMID 35169832, 2022). "P1 was enriched for cell cycle genes (e.g., TOP2A, UBE2C, CKS2), thus defined as cycling tumor cells." (PMID 35860547, 2022). "We selected four LLPS-related hub genes (FAM204A, SMU1, TNPO1 and TOP2A) involved in LPRS to test their transcript levels in cell lines, LGG tissues and non-tumor brain tissues." (PMID 35093128, 2022). "Age, tumor grade, tumor size, receptor status (ER, PR, HER2, Ki-67, TOP2A), and test biomarker expression were evaluated." (PMID 36532641, 2022). "Genes such as TOP2A and MKI67 were found in MP6, indicating that this MP is related to the proliferation of tumor cells." (PMID 36423636, 2022). "Tumor cells can be divided into 4 different subtypes, including basaloid cells (KRT5, KRT14), myoepithelial cells (ACTA2, MYL), cycling cells (MKI67, TOP2A) and duct-like cells (KRT7, KRT19)." (PMID 35860547, 2022). "We found a positive correlation between neutrophils infiltration and TOP2A expression in the case of BLCA, BRCA, BRCA-Basal, COAD, KICH, KIRC, KIRP, LIHC, OV as well as PAAD, hinting the probability of neutrophils’ tumor-promoting role in above tumor types." (PMID 35778520, 2022). "The expression of marker genes of C6 cluster cells, including a total of 276 genes such as TOP2A, MKI67, and TK1, was higher in tumor tissues than in normal tissues from TCGA database." (PMID 36046337, 2022). "The correlation between TOP2A and CDK1 remained significant in both the tumour subtypes (r:0.58, p:0.004; r:0.79, p:0.02 in proliferative, and normal-like subtypes, respectively)." (PMID 36345011, 2022). "The remaining 3 genes (CBX7, TOP2A and BIRC5) filled the gaps of tumour cell regulation in stem cell, epigenetic, genomic instability, proliferation and differentiation." (PMID 35326543, 2022). "The hub genes TOP2A, CDK1, and BIRC5 formed the top cluster with expression in 80–90% of the tumours." (PMID 36345011, 2022). "Similar to TOP2A, KIF11, acting as an oncogene that promotes the proliferation of tumor cells, is negatively correlated with decreased overall survival." (PMID 36589233, 2022). "Compared with non-tumor brain tissue, the transcription levels of FAM204A and SMU1 in LGG tissues decreased, while the transcription levels of NPO1 and TOP2A increased." (PMID 35093128, 2022). "It is noteworthy that the mRNA expressions of TOP2A and TOP1MT were upregulated progressively with advancing stage in many tumor types." (PMID 36288358, 2022).
tumor (continued). "We found that four of the hub genes (TOP2A, AURKA, NEK2, and RACGAP1) can serve as tumor therapeutic targets for drugs approved by FDA." (PMID 33946043, 2021). "TOP2A and CEP55 interacted significantly within the network, and based on the data from GEPIA, TOP2A was more upregulated than CEP55 in tumor samples." (PMID 34787052, 2021). "For tumor stage, significant differences among stage 1, stage 2, and stage 3 were shown in NDC80, CCNB1, KIF20A, DTL, and TOP2A of the key genes from Jia Liver data set (P < 0.05)." (PMID 34746301, 2021). "Expression of the G2/M checkpoint protein p21 increased in tumours treated with ATR inhibitor, while levels of both Top2A and the apoptosis inhibitor Survivin decreased, in agreement with RNA levels." (PMID 34819497, 2021). "Tumor cells that establish themselves in the neuronal niche upregulate PD-1, EGFR, TOP2A, TOPO1 GABA-R, GLUT-R, TrkB, and P75NTK as well as miRNA expression, mutations, and specific epigenetic changes." (PMID 31900168, 2020). "Four proteins were found differentially expressed in KRAS-mutant as compared to wild-type tumours (overexpressed in mutant: KRAS, EGFR; overexpressed in wild-type: TOPO1, TOP2A)." (PMID 31537838, 2019). "ROC curve analysis indicates that PRC1 (P < 0.001, area under curve [AUC] = 0.976, 95%CI = 0.962-0.989) and TOP2A (P < 0.001, AUC = 0.978, 95%CI = 0.965-0.991) performed well in discriminate the HBV-related HCC tumor and adjacent normal tissue." (PMID 31737106, 2019). "As cell-cycle dependent proteins with interrelated functions, TOP2A, TPX2, and ASPM play key roles in the mitotic machinery that drives tumor cell replication in NSCLC and other tumor types." (PMID 31816603, 2019). "The TOP2A staining score was also significantly higher in high-grade tumor (1.67 ± 0.74) and MIBC tumor (1.56 ± 0.49) than low- grade tumor (1.11 ± 0.43, P < 0.001) and NMIBC tumor (1.27 ± 0.45, P < 0.001), respectively." (PMID 31216997, 2019). "The upregulation of TOP2A and its prognostic value have been reported in HCC in previous studies, which also revealed its correlation with tumor onset and chemoresistance." (PMID 31886163, 2019). "Comparison of gene expression in TCGA cohort HCC samples also showed that PRC1 and TOP2A were significant up-regulation in HCC tumor tissues and up-regulation in advance tumor stage tumor tissues." (PMID 31737106, 2019). "The expression of PRC1 and TOP2A also showed a strong correlation in HCC samples from TCGA (r = 0.922, P < 0.0001 for HCC tumor tissues, and r =0.842, P <0.0001 for adjacent normal tissues)." (PMID 31737106, 2019). "The present analysis showed, for the first time, that the anti-tumor effect of fisetin was mediated mainly through activation of CDKN1A, SEMA3E, GADD45B and GADD45A and down-regulation of TOP2A, KIF20A, CCNB2 and CCNB1 genes." (PMID 28052097, 2017). "We observed that knockdown of RNF168 in the tumour cell lines T47D and MDA-MB-231 restrained ubiquitylation of their endogenous TOP2α." (PMID 27558965, 2016). "HER2-related gene CN clusters showed the expected strong associations with menopausal and tumor hormonal status, histological grade, tumor HER2 and TOP2A FISH status, and, with HER2-positive subtypes." (PMID 25098819, 2014). "After three cycles of AT, co-amplification of HER2 and TOP2A in CTCs was observed in one patient with HER2 and TOP2A- tumor." (PMID 22554015, 2012).